PHF1 (PHD finger protein 1)
Diseases named in the same sentence as PHF1 in open-access papers (continued):
Sharing a sentence is not in itself a finding about the gene and the disease.
sarcoma (3 papers, 2018 to 2020). A usually aggressive malignant neoplasm of the soft tissue or bone. "As seen in the LG-ESS, OFMT, and cardiac ossifying sarcomas analyzed so far, the rearrangements of PHF1 as the 3′- partner have breakpoints in exon 2 leading to retention of most of the gene sequence." (PMID 29721194, 2018). "The fact that all detected alterations of PHF1 are similar makes it likely that the gene is a key player in the tumorigenesis of these sarcoma subgroups." (PMID 29721194, 2018). "In addition, low-grade endometrial stroma sarcoma harbors specific chromosomal rearrangements involving JAZF1 and PHF1." (PMID 31309284, 2020).
amyloid (2 papers, 2019 to 2023). "While cell density was lowest near the PHF-1+ cells, Microglia/macrophages were at the highest density around amyloid-plaques, and the density decreased nearly proportional to the distance from the plaque." (PMID 36934255, 2023). "Sections from 3 mice per group were examined using double-labeling for PHF-1 and pS199 tau along with Amylo-Glo, a Thioflavin S analog that labels the beta-pleated sheet confirmation of amyloid plaques." (PMID 31847886, 2019).
Brain atrophy (2 papers, 2022 to 2024). Partial or complete wasting (loss) of brain tissue that was once present. "Only pS396-tau and Oligo-tau forms in the retina correlated with brain Aβ plaque burden, and retinal mature tau tangles, recognized by PHF-1 and MC-1 antibodies, correlated with brain atrophy." (PMID 38980423, 2024).
cognitive decline (2 papers, 2013 to 2025). "To assess whether these brains exhibited other early- or late-stage p-Tau markers, we examined two additional phosphorylated tau proteins: CP13, associated with early (pre-tangle) AD pathology, and PHF1, which appears at later stages of cognitive decline of AD." (PMID 41023469, 2025). "Aβ activates Abl and induces p-Tau suggesting that Abl participates in Aβ-induced p-Tau, while Imatinib reduces AT8 and PHF1 levels of p-Tau and reverses cognitive decline in AD mice." (PMID 23737459, 2013).
fibromyxoid tumor (2 papers, 2015 to 2021). A soft tissue tumor of uncertain lineage characterized by the presence of neoplastic spindle-shaped to round cells in a fibromyxoid stroma. "Interestingly, the ESN showed focal peripheral ossification, a rare feature of ESN and/or LG‐ESS but a hallmark of ossifying fibromyxoid tumors with which they may share also other molecular events such as PHF1 fusions, that is, EP400/PHF1, MEAF6/PHF1, and EPC1/PHF1." (PMID 33099834, 2021).
frontotemporal dementia (2 papers, 2013 to 2017). Frontotemporal dementia (FTD) comprises a group of neurodegenerative disorders, characterized by progressive changes in behavior, executive dysfunction and language impairment, as a result of degeneration of the medial prefrontal and frontoinsular cortices. "Weekly intraperitoneal injections (250 μg) of MC1, DA31 or PHF1 were administered to different cohorts of mice carrying the P301L tau mutation responsible for frontotemporal dementia in humans." (PMID 23638068, 2013). "Importantly, Armanezumab recognized pathological tau in cortices not only from AD cases but also from Frontotemporal Dementia and Pick’s Disease, similarly to other antibodies specific to pathological or total tau, such as PHF1, AT8, AT100, HT7 and TNT-1." (PMID 28472993, 2017).
memory impairment (2 papers, 2016 to 2022). "Excessive tau phosphorylation at Thr23 (AT-180) and Ser396/Ser404 (PHF1) has been found in AD patients’ brains, which inhibits physiological tau binding to microtubules, resulting in memory impairment." (PMID 34958017, 2022). "As reported, the pathologic hyperphosphorylation of tau detected by CP13, PHF1, and AT180 antibodies was found to be increased in the 3xTg-AD mice showing memory impairment." (PMID 27834631, 2016).
Neurofibrillary tangles (2 papers, 2020 to 2021). Pathological protein aggregates formed by hyperphosphorylation of a microtubule-associated protein known as tau, causing it to aggregate in an insoluble form. "The PHF1 antibody recognizes neurofibrillary tangle (NFT) phospho-epitopes on serine 396 and serine 404 that abolish the ability of tau to bind microtubules." (PMID 34744620, 2021). "However, there was a trend toward decrease in the PHF1 epitope after IL-4 injection (P = 0.1), which identifies the late-stage neurofibrillary tangle (NFT) phospho-tau sites Ser396 and Ser404." (PMID 32528242, 2020).
proteinopathies (2 papers, 2022 to 2025). "Moreover, PHF-1 promotes specific three-layered β-strand folds that are different from other tau conformations, suggesting a distinct pathological entity with unique properties that could facilitate co-occurrence detection with other proteinopathies, including TDP-43." (PMID 40722308, 2025). "The neuronal features that were imaged here are from those surviving neurons that have endured AD, including non-proteopathy bearing (PHF1-TAU and Aβ negative) and proteopathy-bearing neurons (PHF1-TAU or Aβ positive)." (PMID 36333818, 2022).
schizophrenia (2 papers, 2017 to 2021). A major psychotic disorder characterized by abnormalities in the perception or expression of reality. "For the schizophrenia patients who had survived at least 40 years after leucotomy in this study, we similarly noted NFTs, astrocytic tangles and p-tau immunoreactive cell processes in neuroanatomical areas near the axotomy site, with three p-tau antibodies including PHF1." (PMID 27885490, 2017).
Soft Tissue Tumors (2 papers, 2018 to 2024). "In this regard, PHF1 and the tumors characterized by its rearrangement do not differ principally from Soft Tissue Tumors in general where similar situations are known to be common." (PMID 29721194, 2018).
status epilepticus (2 papers, 2019 to 2025). Status epilepticus is defined as a continuous seizure lasting more than 30 min, or two or more seizures without full recovery of consciousness between any of them. "Tau phosphorylation at 1–24 h time-points post-status epilepticus was most prominent on serine/threonine 202/205 (AT8) compared to serine 396/404 (PHF-1) with only AT8 phospho-tau increased in epileptic mice at 14 days." (PMID 31780921, 2019). "In experimental models of TLE, pTau with AT100, PHF1, and CP13 was shown, whereas in status epilepticus a reduction of AT8 in the chronic stages and no changes with AT180 were noted." (PMID 40299318, 2025).
asthma (1 paper, 2024). "A SNP (rs1046295) associated with asthma was revealed within the OCT1-binding site of PHF1 gene." (PMID 38254723, 2024).
brain injury (1 paper, 2025). Acute and chronic (see also brain INJURIES, CHRONIC) injuries to the brain, including the cerebral hemispheres, CEREBELLUM, and brain STEM. "In a rodent model of repetitive mild traumatic brain injury (rmTBI), psilocybin administration reduced phosphorylated Tau (PHF-1 epitope) levels in the soluble fraction and showed a downward trend in insoluble aggregated Tau." (PMID 40806766, 2025).
breast tumor (1 paper, 2022). "The negative correlation between CTR9 and PRC2.1 facultative subunits (PHF1/MTF2/PHF19 and EPOP) at the mRNA level was also observed in 817 ER-positive primary breast tumor samples in TCGA." (PMID 35137163, 2022).
chondroid syringomas (1 paper, 2022). "Recently, a new gene fusion of plant homeodomain (PHD) finger protein 1 gene (PHF1) to TFE3 was identified in a malignant chondroid syringoma." (PMID 35225876, 2022). "Based on this finding, the authors postulated that there might be a genetic link between malignant chondroid syringomas and PHF1 or TFE3 altered tumors." (PMID 35225876, 2022).
colon adenocarcinoma (1 paper, 2023). "For example, a high PHF1 expression is linked to a worse prognosis in colon adenocarcinoma (COAD) but a better prognosis in pancreatic cancer." (PMID 37107696, 2023).
Down syndrome (1 paper, 2022). "This phenomenon has also been observed close to PHF-1+ neurons in AD27 and Down syndrome patients." (PMID 35136118, 2022).
lung carcinoma (1 paper, 2022). "To further evaluate the in vivo effect of PHF1 on regulating cell growth, we utilized the PHF1-deficient A549 cells and parental cells to construct the orthotopic lung cancer model." (PMID 35945194, 2022).
malignant melanoma (1 paper, 2018). "When tested against human malignant melanoma A375 cell line, PHF1 exhibited higher inhibitory activity (61.88%) with an IC50 value of 199.13 μg/mL, than PHF2." (PMID 29378653, 2018). "Since PHF1 was also cytotoxic against malignant melanoma cells, it has the potential to be developed as an anti-cancer agent with further studies." (PMID 29378653, 2018). "Moreover, PHF1 holds promise as a potential anti-cancer agent in the treatment of malignant melanoma." (PMID 29378653, 2018).
MTHFR deficiency (1 paper, 2014). "The PHF-1 is considered a late phospho-Tau epitope in AD, and PP2A methylation regulates many other “earlier” Tau phosphorylation sites that could be potentially sensitive to the effects of mild MTHFR deficiency in young animals." (PMID 25202269, 2014).
Obesity (1 paper, 2022). Accumulation of substantial excess body fat. "In a study that examined the association between obesity and DNA methylation in NHB and NHW women diagnosed with breast cancer, the authors detected interactions with ER status (PSMB1, QSOX1, and PHF1) and race (TOMM20) among the top 20 obesity-associated CpG cites." (PMID 35752704, 2022).
ovarian tumors (1 paper, 2020). "A break-apart FISH assay for BCOR, PHF1, and JAZF1 was negative in all components of the ovarian tumors." (PMID 32290854, 2020).
scrapie (1 paper, 2015). A fatal disease of the nervous system in sheep and goats, characterized by pruritus, debility, and locomotor incoordination. "Of the scrapie-infected mouse brains, the amount of P-Tau was greatest in 139A followed by ME7 and then 22L, although the differences were not significant (p>0.05) when Mab CP13 was used for immunostaining, but were significant p<0.05) when Mab PHF1 was used to compare the three scrapie strains." (PMID 26630676, 2015). "We measured the levels of T-Tau (Mab DA31) and P-Tau (Mabs CP13 and PHF1) in the brains of uninfected C57Bl mice and three mouse-adapted scrapie strain-infected mice using the EIMAF (Enhanced Immunoassay using Multi-Arrayed Fiberoptics) technology to achieve an accurate and quantitative assessment." (PMID 26630676, 2015).
skin aging (1 paper, 2018). The gradual irreversible changes in structure of skin that occur as a result of the passage of time.. "In conclusion, the anti-oxidant capacity of phytochemicals present in the leaves of Nyctanthes arbor-tristis and PHF1 can be used as a potential agent to prevent skin aging and restore skin elasticity." (PMID 29378653, 2018).
uterine sarcoma (1 paper, 2025). "LGESS is the second most common uterine sarcoma after LMS and is reportedly characterized by specific gene rearrangements such as JAZF1::SUZ12, JAZF1::PHF1, and EPC1::PHF1." (PMID 40072062, 2025).
uterine tumors (1 paper, 2022). "It is currently unknown why these fusions are associated with uterine tumors, let alone with new pathogenic subgroups of ESS, but it is intriguing that two of these known JAZF1 fusions (with PHF1 or SUZ12) could directly alter PRC2 function." (PMID 35328741, 2022).
tumor (19 papers, 2012 to 2025). "Expectedly, after 8 weeks, PHF1 deficiency remarkably enhanced growth of orthotopic lung tumors, as indicated by the bioluminescence signals and numbers of tumor nodes." (PMID 35945194, 2022). "Both Trps1 and Phf1 have tumor suppressor properties, are associated with repressive chromatin and are up-regulated outside WOS." (PMID 35087569, 2021). "Lastly, we utilized the H1299 cells to establish subcutaneous tumor model and found that FOXM1 inhibitor, RCM-1, could significantly suppress the in vivo growth of tumors derived from the PHF1-deficient cells, as evidenced and compared by tumor volumes." (PMID 35945194, 2022). "In conclusion, these data supported that FTO exerted the anti-tumor effect and PHF1 overexpression could reverse the tumor progression of FTO-deficient LUAD in vitro and in vivo." (PMID 35945194, 2022). "Therefore, PHF1′s tumor-suppressive role may also be linked to its ability to suppress DNA damage and thereby prevent harmful chromosome rearrangement." (PMID 37107696, 2023). "The downregulation of the FTO/PHF1 axis promotes tumor cell self-renewal, progression, and poor prognosis by enhancing FOXM1 expression, thereby compromising therapeutic efficacy." (PMID 40823093, 2025). "Additional fluorescence in situ hybridization examination of the primary tumor cells demonstrated PHF-1 rearrangement." (PMID 40151688, 2025). "In lung adenocarcinoma (LUAD), FTO stabilizes PHF1 mRNA through demethylation, forming a tumor-suppressive axis." (PMID 40823093, 2025). "PHF1 gene plays a role in regulating gene transcription and is involved in variable neoplasms with its fusion partners." (PMID 35225876, 2022). "Taken together, our findings indicated that down-regulated FTO/PHF1 axis triggered the tumor stemness features to drive progression by activating FOXM1." (PMID 35945194, 2022). "Given that intensive documents revealed that stemness features robustly contribute to tumor progression and drug resistance of LUAD, we intended to explore the relationships between PHF1 and tumor stemness capacity." (PMID 35945194, 2022). "Collectively, our findings revealed that FTO positively regulates PHF1 expression and determined the tumor-suppressive role of FTO/PHF1 axis, thereby highlighting insights into its epigenetic remodeling mechanisms in LUAD progression and treatment." (PMID 35945194, 2022). "Recently, an ESN with MEAF6/PHF1 was reported, providing further support for a continuum between these two tumor entities." (PMID 33099834, 2021). "It is now established that it is a translocation related tumor, most often marked by translocation of PHF1 gene." (PMID 29299229, 2017). "5′-RACE, RT-PCR, and sequencing showed the presence of an MEAF6-PHF1 chimera in the tumor with exon 5 of MEAF6 being fused in-frame to exon 2 of PHF1 so that the entire PHF1 coding region becomes the 3′ terminal part of the MEAF6-PHF1 fusion." (PMID 22761769, 2012). "Thus, although these data globally support a tumor-suppressive role of PHF1, an oncogenic role of PHF19, and a relatively neutral role of MTF2, the three PCL proteins appear to have individual impacts dependent on the cancer type." (PMID 37107696, 2023). "In line with the in vitro findings, FTO inhibition induced growth rates of tumors relative to control tumors, whereas PHF1 overexpression could attenuate the elevated growth, as quantified and compared by the tumor volumes and tumor weight." (PMID 35945194, 2022).
tumor (continued). "To determine whether PHF1 is an epigenetic regulator with clinical significance, we firstly conducted the differential analysis in TCGA-LUAD (N = 483) and GSE68465 (N = 443) datasets, where PHF1 was found to be significantly lower in tumor samples than normal tissues." (PMID 35945194, 2022). "The review delves into the oncogenic potential of certain PHD finger proteins, exemplified by PHF1 and PHF8, which promote tumor progression through epigenetic dysregulation and modulation of signaling pathways like Wnt and TGFβ." (PMID 38813086, 2024). "To further investigate the in vivo roles of FTO/PHF1 axis in LUAD, we utilized the modified H1299 cells to perform the subcutaneous tumor model incorporating three groups (shCtrl+vector, shFTO+vector, shFTO+PHF1)." (PMID 35945194, 2022). "PHF1, RUFY1, and CDR2 are highly expressed in some cancers, positively correlated with tumor progression." (PMID 34571936, 2021). "Additional fluorescence in situ hybridization (FISH) for PHF-1 in the primary tumor, using the ZytoLight SPEC PHF-1 dual-color break-apart probe (ZytoVision, Bremerhaven, Germany), demonstrated break-apart signals in 68% of the tumor nuclei (70/102)." (PMID 40151688, 2025). "In this study, we found that PHF1 expressed lowly in LUAD, which was a tumor suppressor." (PMID 35945194, 2022). "Genetic abnormalities may be involved in pathogenesis; however, currently, only one case with a fusion of the genes PHF1 (PHD finger protein 1) and TFE3 (transcription factor E3), commonly found in other neoplasms, has been reported." (PMID 34064849, 2021). "The second tumor harboring a MDM2 amplification had high‐grade morphology, polysomy of JAZF1, PHF1, and YWHAE but no rearrangements were reported, leading to a diagnosis of UUS." (PMID 32352245, 2020).